CCNK (cyclin K)
Description:
Regulatory subunit of cyclin-dependent kinases that mediates activation of target kinases. Plays a role in transcriptional regulation via its role in regulating the phosphorylation of the C-terminal domain (CTD) of the large subunit of RNA polymerase II (POLR2A).
Synonyms: CPR4; IDDHDF
Tractability: Small molecule: a structure with a bound ligand is known; a high-quality ligand is known. PROTAC: ubiquitination databases record sites on it; its protein half-life has been measured.
Target class: Kinase; Protein kinase regulatory subunit; Enzyme
Gene: Protein-coding gene on chromosome 14 (99,481,169 to 99,535,044, forward strand). Ensembl gene ENSG00000090061.
Subcellular location: Nucleus
Subcellular location (Human Protein Atlas): Nucleoplasm
Pathways (Reactome):
Gene expression (Transcription): Formation of RNA Pol II elongation complex; RNA Polymerase II Pre-transcription Events; RNA Polymerase II Transcription Elongation; RNA polymerase II transcribes snRNA genes
Disease: Formation of HIV elongation complex in the absence of HIV Tat; HIV elongation arrest and recovery; Pausing and recovery of HIV elongation
Signal Transduction: SMAD2/SMAD3:SMAD4 heterotrimer regulates transcription
Gene Ontology:
Molecular function: cyclin-dependent protein serine/threonine kinase activity; protein binding; protein kinase binding; RNA polymerase II CTD heptapeptide repeat kinase activity; cyclin-dependent protein serine/threonine kinase activator activity; cyclin-dependent protein serine/threonine kinase regulator activity
Biological process: DNA damage response; host-mediated suppression of viral genome replication; positive regulation of transcription elongation by RNA polymerase II; regulation of signal transduction; transcription by RNA polymerase II; positive regulation of DNA-templated transcription, elongation; positive regulation of transcription by RNA polymerase II; regulation of cyclin-dependent protein serine/threonine kinase activity; regulation of cell cycle; regulation of transcription by RNA polymerase II
Cellular component: cyclin K-CDK12 complex; cyclin K-CDK13 complex; nucleoplasm; cyclin/CDK positive transcription elongation factor complex; nucleus
Genetic constraint (gnomAD): Loss-of-function variants: 8 observed, 42.46 expected, observed/expected ratio (o/e) 0.19, 90% interval 0.11 to 0.34. The upper end of that interval is the gene's LOEUF score, 0.34, which puts it in group 1 of 6, group 1 being the genes least tolerant of losing a copy. Missense variants: 342 observed, 459.62 expected, observed/expected ratio (o/e) 0.74, 90% interval 0.68 to 0.81. Synonymous variants: 196 observed, 182.22 expected, observed/expected ratio (o/e) 1.08, 90% interval 0.96 to 1.21.
Homologues: Orthologues: macaque CCNK (100% identical), mouse Ccnk (96% identical), dog CCNK (96% identical), guinea pig CCNK (96% identical), pig CCNK (96% identical), rat Ccnk (96% identical), chimpanzee CCNK (94% identical), rabbit CCNK (82% identical), tropical clawed frog ccnk (81% identical), Drosophila melanogaster CycK (37% identical), Caenorhabditis elegans ccnk-1 (18% identical). Paralogues in human: CCNT1 (23% identical), CCNT2 (23% identical), CCNL1 (18% identical), CCNL2 (17% identical), CCNH (11% identical), CCNQ (10% identical).
Diseases named in the same sentence as CCNK in open-access papers:
CCNK is named in the same sentence as 46 diseases in open-access papers, as found by Europe PMC text mining. Sharing a sentence is not in itself a finding about the gene and the disease. The quoted sentences say what the papers report.
prostate carcinoma (5 papers, 2020 to 2025). A carcinoma that arises from epithelial cells of the prostate gland. "Cyclin K loss in prostate cancer drives androgen receptor (AR) variant expression and therapy resistance, inducing a BRCA-like deficiency (BRCAness) that increases sensitivity to PARP inhibitors, making it a key target in advanced prostate cancer." (PMID 40075638, 2025). "As shown in another study, Cyclin K expression was markedly enhanced in primary prostate cancer, and the increased expression of Cyclin K was associated with decreased biochemical recurrence-free survival." (PMID 37626854, 2023). "In prostate cancer, cyclin K was shown to mediate proliferation and inhibit apoptosis likely through AURKB." (PMID 33915740, 2021). "For example, Cyclin K regulates Aurora B expression to affect apoptosis and proliferation by inducing mitotic catastrophe in prostate cancer." (PMID 33042275, 2020). "They found that Cyclin K was required for prostate cancer cell growth." (PMID 37626854, 2023). "They further pointed out that Cyclin K could be used as an independent biomarker for predicting biochemical recurrence-free survival for patients with prostate cancer." (PMID 37626854, 2023).
colorectal cancer (4 papers, 2022 to 2024). A primary or metastatic malignant neoplasm that affects the colon or rectum. "Demonstrated that the targeted degradation of CCNK/CDK12 complex is a druggable vulnerability of colorectal cancer." (PMID 38459430, 2024). "On the other hand, degradation of CCNK/CDK12 in colorectal cancer inhibits cancer cell proliferation and growth in vivo." (PMID 36374405, 2023). "Moreover, the genetic or pharmaceutical ablation of Cyclin K restricted colorectal cancer growth in cell line-derived xenograft (CDX) and patient-derived xenograft (PDX) models." (PMID 37626854, 2023). "Targeting CCNK/CDK12 degradation might regulated colorectal cancer." (PMID 36463205, 2022).
lung carcinoma (4 papers, 2020 to 2025). "To elucidate the underlying mechanisms by which Cyclin K functions in lung cancer, we performed RNA sequencing (RNA-Seq) in A549 cells transfected with scrambled or Cyclin K siRNA." (PMID 33042275, 2020). "In our study, we uncovered for the first time that Cyclin K is frequently overproduced in lung cancer and is associated with overall survival in lung cancer patients." (PMID 33042275, 2020). "Cyclin K’s oncogenic significance and importance as a possible biomarker for tumor development and treatment resistance were supported by their investigation, which showed that it is overexpressed in lung cancer tissues and linked to a poor prognosis." (PMID 40075638, 2025). "Loss of Cyclin K or Cyclin D1 markedly suppressed lung cancer cell growth and proliferation." (PMID 33042275, 2020). "Silencing cyclin K disrupts the G2/M checkpoint, impairing tumor growth and increasing radiosensitivity, highlighting its therapeutic potential in lung cancer." (PMID 40075638, 2025). "In lung cancer, cyclin K stabilizes β-catenin and drives cyclin D1 expression, enhancing tumor proliferation and radioresistance." (PMID 40075638, 2025). "They demonstrated that cyclin K overexpression correlates with poor prognosis in patients with lung cancer." (PMID 40075638, 2025). "It was further demonstrated that Cyclin D1 partially mediated the biological function of Cyclin K in lung cancer cells." (PMID 37626854, 2023). "Taken together, these data support the oncogenic role of Cyclin K and indicate that Cyclin K silencing suppresses tumorigenesis in lung cancer both in vitro and in vivo." (PMID 33042275, 2020). "In our research, we show that Cyclin K is overexpressed and promotes tumorigenesis and radioresistance in lung cancer both in vitro and in vivo." (PMID 33042275, 2020). "More importantly, we also revealed a novel role for Cyclin K in the regulation of lung cancer radioresistance." (PMID 33042275, 2020). "In this study, we found that Cyclin K is overexpressed in lung cancer patients, and high levels of Cyclin K predict poor prognosis." (PMID 33042275, 2020). "To investigate Cyclin K expression in lung cancer, we first analyzed Cyclin K mRNA levels in lung adenocarcinoma and adjacent normal lung tissue using TCGA and the Oncomine database." (PMID 33042275, 2020). "This study aimed to investigate the role and regulatory mechanism of Cyclin K in lung cancer radioresistance." (PMID 33042275, 2020). "Functionally, we demonstrate that Cyclin K depletion results in reduced proliferation, defective G2/M checkpoint and enhanced radiosensitivity in lung cancer." (PMID 33042275, 2020). "More importantly, we show that Cyclin D1 is the major effector that mediates the biological functions of Cyclin K in lung cancer." (PMID 33042275, 2020). "We also provided strong evidence that Cyclin K knockdown impairs tumorigenesis and radioresistance in lung cancer both in vitro and in vivo through attenuating Wnt/β-catenin signaling." (PMID 33042275, 2020). "To exclude any off-target effects of Cyclin K siRNA and to further confirm the roles of Cyclin K in lung cancer, we generated a Cyclin K siRNA resistant plasmid (SFB-Cyclin K-R)." (PMID 33042275, 2020). "Collectively, these results indicate that Cyclin K interacts with and promotes the stabilization of β-catenin, thereby upregulating the expression of Cyclin D1 and facilitating DNA repair in lung cancer." (PMID 33042275, 2020). "Taken together, our work supports the notion that Cyclin K exerts its biological functions primarily through regulating Cyclin D1 in lung cancer cells." (PMID 33042275, 2020). "Both tumor size and weight from mice injected with Cyclin K stable knockdown lung cancer cells were substantially decreased compared to those injected with control cells." (PMID 33042275, 2020). "Furthermore, reduced cyclin K expression was shown to decrease proliferation and increase sensitivity to radiation in lung cancer." (PMID 40075638, 2025).
lung carcinoma (continued). "To test this hypothesis, we first knocked down the expression of Cyclin K in two different lung cancer cell lines using siRNAs and found that depletion of Cyclin K impaired tumor cell growth and colony formation ability." (PMID 33042275, 2020). "Cyclin K was overexpressed in lung cancer tissues compared to adjacent normal tissues." (PMID 33042275, 2020). "Furthermore, bioinformatics analysis with TCGA database demonstrated that Cyclin K expression is positively correlated with both β-catenin and Cyclin D1 levels in lung cancer tissues." (PMID 33042275, 2020). "Cyclin K expression was upregulated in lung cancer tissues compared to normal lung tissues." (PMID 33042275, 2020). "Due to the overexpression of Cyclin K in lung cancer, we speculated that Cyclin K might function as an oncoprotein." (PMID 33042275, 2020). "Notably, our results demonstrated that further inhibition of Cyclin K with siRNA in lung cancer cells led to insignificant effects on these phenotypes when Cyclin D1 was simultaneously knocked down." (PMID 33042275, 2020). "Therefore, our data indicate that Cyclin K plays pivotal roles in promoting tumorigenesis and radioresistance in lung cancer." (PMID 33042275, 2020). "Their findings indicated that these mitotic defects might be a consequence of the Cyclin K depletion-mediated transcriptional downregulation of Aurora B. Additionally, the knockdown of Cyclin K suppressed lung cancer cell proliferation, both in vitro and in vivo." (PMID 37626854, 2023). "Given that Cyclin K is overexpressed in lung cancer tissues and is related to radioresistance, it may represent a promising therapeutic biomarker for cancer radiotherapy, especially in lung cancer." (PMID 33042275, 2020). "Furthermore, we revealed that the β-catenin target gene Cyclin D1 is an essential downstream effector that mediates the biological effects of Cyclin K, implying that the Cyclin K/β-catenin/Cyclin D1 pathway represents a potential therapeutic target in lung cancer." (PMID 33042275, 2020). "Inhibition of Cyclin K with siRNA significantly reduced basal expression levels of Cyclin D1 and GNG3, while increasing expression levels of PCDH9, WNT9A and GNG7 in two different lung cancer cell lines." (PMID 33042275, 2020). "However, the role and regulatory mechanism of Cyclin K in lung cancer radioresistance have not been characterized." (PMID 33042275, 2020).
ovarian carcinoma (4 papers, 2015 to 2025). A malignant neoplasm originating from the surface ovarian epithelium. "For example, loss of CDK12/cyclin K-mediated transcriptional elongation of genes in the HR DNA repair pathway, including BRCA1, has previously been demonstrated in ovarian cancers." (PMID 40504161, 2025). "For instance, in ovarian cancer, CDK12 loss downregulates transcripts in the HR DNA repair pathway—a phenotype attributed to reduced CDK12/cyclin K-mediated transcriptional elongation of the corresponding genes." (PMID 39368479, 2024).
breast carcinoma (3 papers, 2022 to 2025). "The oncogenic role of CCNK is further supported by additional research on breast cancer." (PMID 40075638, 2025).
leukemia (3 papers, 2020 to 2022). A malignant (clonal) hematologic disorder, involving hematopoietic stem cells and characterized by the presence of primitive or atypical myeloid or lymphoid cells in the bone marrow and the blood. "Recently, the H3K4 methyltransferase SETD1A has been proposed to regulate the expression of genes involved in DNA damage response by interacting with cyclin K, and this interaction is required for leukemia cell growth." (PMID 33042275, 2020). "To evaluate the roles of WDR82 complexes and cyclin K complexes in human leukemia cells, we performed a CRISPR functional assay against these complex subunits and confirmed the strong dependency on WDR82, cyclin K, and their binding partners." (PMID 36450243, 2022).
lung adenocarcinoma (3 papers, 2020 to 2025). A carcinoma that arises from the lung and is characterized by the presence of malignant glandular epithelial cells. "Given the limited availability of studies on CCNK in endometrial cancer, we compare our findings with data from other cancers, such as lung adenocarcinoma, to gain a more comprehensive understanding of the role of CCNK at both the mRNA and protein levels in tumor progression." (PMID 40075638, 2025). "To further examine whether Cyclin K expression was indeed increased, we measured Cyclin K protein levels in lung adenocarcinoma tissue arrays." (PMID 33042275, 2020).
colon cancer (2 papers, 2024 to 2025). "Cancer stemness was suppressed by dinaciclib or THZ531 treatment, or knockdown of CCNK; hence, CDK12 inhibitors are potential chemotherapeutic agents against colon cancer." (PMID 38182897, 2024). "As Cyclin K is the regulatory subunit of the CDK12 kinase, we would expect that the CCNK gene that encodes Cyclin K would be strongly upregulated in the breast tumor but not necessarily in the colon tumor." (PMID 39946483, 2025).
glioblastoma (2 papers, 2023). The most malignant astrocytic tumor (WHO grade IV). "Based on the TCGA and GTEx data from the public cancer portal, GEPIA2, Cyclin K mRNA expression is increased in several types of cancers, including cholangiocarcinoma, esophageal carcinoma, glioblastoma, low-grade glioma, pancreatic adenocarcinoma, stomach adenocarcinoma, and thymoma." (PMID 37626854, 2023).
invasive breast ductal carcinoma (2 papers, 2018 to 2023). "In our pilot study, we examined cyclin K expression in human invasive breast ductal carcinoma." (PMID 29760377, 2018).
testicular cancer (2 papers, 2014 to 2023). A primary or metastatic malignant neoplasm that affects the testis. "Knockdown of cyclin K in a testicular cancer cell line markedly reduces cell proliferation." (PMID 25004108, 2014). "In addition, we found that cyclin K is highly expressed in human testicular cancers." (PMID 25004108, 2014).
colorectal tumor (1 paper, 2023). "The pharmaceutical degradation of Cyclin K by the molecular glue NCT02 also sensitized colorectal tumor spheroid culture cells, such as oxaliplatin and irinotecan, to chemotherapy." (PMID 37626854, 2023).
cyst (1 paper, 2012). A sac-like closed membranous structure that may be empty or contain fluid or amorphous material. "In vitro translation data indicated that the template activity of cyclin K mRNA stored in the postdiapause cyst was repressed." (PMID 22363807, 2012).
diffuse large B-cell lymphoma (1 paper, 2024). "On the other hand, CCNK is complexed with kinase CDK12 and CDK13, which are strongly associated with BRCA, AML and diffuse large B-cell lymphoma (DLBCL)." (PMID 38459430, 2024).
endometrial adenocarcinoma (1 paper, 2025). "According to the findings, CCNK immunoreactivity was considerably greater in tumor tissues than in nearby tissues for each of the three endometrial cancer subtypes that was studied: non-endometrioid adenocarcinoma (nEAC), EC, and endometrial adenocarcinoma (EAC)." (PMID 40075638, 2025).
endometrial cancer (1 paper, 2025). Primary or metastatic malignant neoplasm involving the endometrium (mucous membrane that lines the endometrial cavity). "The findings demonstrated that poor clinical outcomes are associated with high CCNK expression, which is prevalent in endometrial cancer tissues." (PMID 40075638, 2025). "Kaplan–Meier survival analysis revealed that CCNK immunohistochemical expression, defined using a cut-off value of 4, demonstrated a potential association with OS in patients with endometrial cancer." (PMID 40075638, 2025). "The analysis of CCNK mRNA expression in endometrial cancer using the Mann–Whitney test in our study revealed subtype-specific patterns." (PMID 40075638, 2025). "Our findings indicate that CCNK expression is elevated in endometrial cancer tissues compared to normal endometrial samples." (PMID 40075638, 2025). "This study examines the expression of cyclin K (CCNK) in endometrial cancer by comparing immunohistochemical analysis (IHC) with gene expression data from The Cancer Genome Atlas (TCGA) across endometrioid and non-endometrioid types and evaluates its correlation with patient survival outcomes." (PMID 40075638, 2025). "Additionally, in silico analysis of data from gene expression analyses were performed using datasets from TCGA, comparing CCNK expression in endometrial cancer samples with normal endometrial tissue." (PMID 40075638, 2025). "In our study, the nuclear expression of CCNK was observed in endometrial cancer, while no expression was detected in normal endometrial tissue." (PMID 40075638, 2025). "However, in the nEAC subtype, tumor tissues had significantly higher levels of CCNK mRNA expression than nearby normal tissues (p = 0.0445), suggesting that CCNK may play a part in the development or progression of the more aggressive non-endometrioid subtype of endometrial cancer." (PMID 40075638, 2025).
endometrioid adenocarcinoma (1 paper, 2025). An adenocarcinoma characterized by the presence of malignant glandular epithelial cells resembling endometrial cells. "In endometrioid carcinoma, strong nuclear overexpression of CCNK was observed in one sample, whereas another demonstrated low nuclear expression." (PMID 40075638, 2025).
endometrioid endometrial carcinoma (1 paper, 2025). "However, a significant association was also found in patients with non-endometrioid endometrial carcinoma, where high CCNK expression correlated with poorer survival (p = 0.01)." (PMID 40075638, 2025).
gastric tumors (1 paper, 2019). "In the gastric tumors, many of these genes are regulated by ETS2, BMP4, and TGFB1 and by the kinases MAPK1(ERK) and CCNK and the transcription regulators E2F, CBX5, and CCND1." (PMID 31584998, 2019).
non-small cell lung carcinoma (1 paper, 2025). A group of at least three distinct histological types of lung cancer, including non-small cell squamous cell carcinoma, adenocarcinoma, and large cell carcinoma. "To date, the CCNK protein has been studied as a potential biomarker among tumors associated with non-small-cell lung cancer, the prostate gland, the testis, and the hematopoietic system." (PMID 40075638, 2025).